RB1 (RB transcriptional corepressor 1)
Diseases named in the same sentence as RB1 in open-access papers (continued):
Sharing a sentence is not in itself a finding about the gene and the disease.
cancer (continued). "Furthermore, familial RB patients with RB1 mutation do not always initiate cancer in both eyes." (PMID 36230849, 2022). "A previous research has shown that RB1-mediated release of IL-6 can promote aging and recruit NKT cells in the radiation response, which is helpful for cancer immune monitoring." (PMID 35299734, 2022). "In many cancer entities, the CDK4/RB1 pathway is disturbed and leads to increased cell proliferation." (PMID 34687436, 2022). "It is found that in 70% of human cancers, and 78% of GBM patients, the RB pathway is disrupted even though only 11% of GBM patients had mutations in the RB1 gene." (PMID 36654821, 2022). "Among 12 genes reported in the literature as SL with RB1 6 genes (PPWD1, SKP2, AURKA, AURKB, E2F1, and E2F3) scored as SL RB1 partners in human cancer patients." (PMID 33591981, 2021). "All the significant nine representative terms covered 16 genes with 6 NCG cancer genes CTNNB1, PML, RB1, MLL2, ARNT and NRIP1 belonging to at least three representative terms." (PMID 34504716, 2021). "As cancer cells with elevated E2F1 activity have been shown to be sensitive to HDAC inhibitor‐induced cell death and RB1 inactivation in RB results in deregulated E2F1 activity, several studies have investigated the effects of HDAC inhibitors on RB cell death." (PMID 31782885, 2020). "This was unexpected, as studies have previously shown that Rb1 deletion results in increased TCA cycle activity and mitochondrial activation in non-cancer tissues in vivo." (PMID 31963621, 2020). "Known cancer genes such as EGFR, EZH2, or CCDN2 were frequently affected by duplications and other known cancer genes such as CDKN2A, RB1, KLK2, or CD79A were frequently affected by deletions." (PMID 32604718, 2020). "A number of studies have been published for expression analysis of RB1 and CCND1 in different cancers including brain cancer." (PMID 32373934, 2020). "Surprisingly, only eight identified genes (CCND1, CDK6, CDKN2A, KDM5A, MDM2, MLL3, PPP2R1A, and RB1) are shared by UniCovEx and CovEx, and they are all NCG cancer genes." (PMID 30828525, 2019). "Using DNA copy number data from 9,744 human cancer specimens, we demonstrate that linear deletion limitation exists and exposes deletion-limiting genes for seven known deletion targets (CDKN2A, RB1, PTEN, MAP2K4, NF1, SMAD4, and LINC00290)." (PMID 31341961, 2019).
cancer (continued). "There are studies reported that miR-93 can promote different cancer cells proliferation, migration and progression by targeting PPARGC1A 24, PTEN 25, RB1 26, TIMP2 27, and so on." (PMID 31737116, 2019). "For six of these, the deletion peaks map to well-known tumor suppressor genes (CDKN2A, PTEN, RB1, MAP2K4, NF1, and SMAD4) that are frequently deleted in multiple cancer types." (PMID 31341961, 2019). "The results confirmed that alterations involving RB1 and NFE2L2 were enriched in basal cancers, whereas alterations involving FGFR3 and KDM6A were enriched in luminal tumors." (PMID 29977169, 2018). "The relatively fast proliferating cancer cell line (A549) used in this study is positive for both PARP1 and RB1 (as confirmed by western blots – PARP1 and chromatin immunoprecipitation in G1 arrested cells – RB1)." (PMID 29306194, 2018). "Therefore, loss of function of ATM or RB1 protein may contribute to reduced DSB repair response and uncontrolled cell proliferation, which can lead to increased cancer susceptibility and vulnerability to radiotherapy or cytotoxic agents, e.g. cisplatin or carboplatin." (PMID 29682192, 2018). "Of note, both in the pan-cancer and in the BC datasets, CCNE1/RB1 performed better than CCNE1 or RB1 alone in predicting palbociclib de novo resistance." (PMID 30511015, 2018). "Previous studies have reported that a variety of genes regulated by CTCF, including RB1, TERT and BAX, are involved in proliferation and apoptosis in cancer cells." (PMID 28977939, 2017). "FNDC3B is contained in the amplified region 3q26.1-q27.2, inducing the epithelial-to-mesenchymal transition (EMT) and activating several cancer pathways, including PI3-kinase/Akt, RB1 and TGFβ signaling." (PMID 26901676, 2016). "Hence, the interdependence of BRG1 on RB1 might be viewed as unimportant to cancer." (PMID 28105458, 2016). "The hubs also include RB1, BCL2, AKT1, CDK2, CASP8 which are involved in mechanisms of apoptosis, to which cells are known to acquire resistance in all types of cancers." (PMID 23166660, 2012).
cancer (continued). "The tumor suppressor pRb plays a key role regulating cell cycle arrest, and disturbances in the RB1 gene have been reported in different cancer forms." (PMID 20594292, 2010). "According to PubMeth, DAPK1, PYCARD, RB1, and TP73 are methylated in at least half of our fourteen cancer models." (PMID 19402918, 2009). "RB1 co-deletion with BRCA2, due to synteny on chromosome 13q, may explain reduced efficacy of CDK4/6 inhibitors in BRCA2 mutant cancers." (PMID 41512445, 2026). "It is possible that RB1 inactivation in these samples plays a noncanonical role outside of E2F-mediated cell-cycle control, as has been suggested for other cancer types that exhibit acquired RB1 alterations later in disease progression." (PMID 39185963, 2025). "However, miR-192 can exhibit dual effects when targeting the same gene in different cancers, such as BCL-2 and RB1." (PMID 40087755, 2025). "In the absence of RB1 defects as a ground truth for these cancers, we assumed that patients with RBness are more likely to exhibit poor clinical outcome than those without RBness." (PMID 40138429, 2025). "To delineate aggressive RBness cancers independent of the bona fide RB1 defects (patients with low Rb or pRb, RB1 MTs, and/or deep deletions), we assessed the outcome of the RBNSig-high group’s patients with RBness (n = 328) independently." (PMID 40138429, 2025). "Our pan-cancer association analysis did not reveal enrichment of AM-1882 sensitivity with other cancer gene alterations (for example, CCNE1, RB1 or BRCA1)." (PMID 38151625, 2024). "Furthermore, AM-1882 is active in a subset of cancer cell lines with CCNE1, BRCA1 and RB1 gene alterations and can enhance apoptosis when combined with PARP inhibition." (PMID 38151625, 2024). "The average abundance of the RB1 protein was greater in cancer cell lines without P16 expression than in those with P16 expression." (PMID 39351198, 2024). "According to The Cancer Genome Atlas and GTEx RNA-seq datasets,40E2F1 expression is consistently correlated with P16 but not RB1 expression in human normal and cancer tissues." (PMID 39351198, 2024). "Among genes (RB1, ERBB2, CTNNB1) identified by method CPGA-SMCMN, although they are not enriched in a biological pathway with any other identified genes, they have been reported to be important cancer related genes." (PMID 37221474, 2023).
cancer (continued). "Prior to categorizing the presence of LGRs across cancer types, to validate the LGR calling method, we used a previously reported copy number sensitive method with ddPCR to detect BRCA1/2 LGRs in 7 samples and RB1 LGRs in eight samples." (PMID 37013911, 2023). "In addition, we identified recurrent CNVs in regions of well-recognized cancer-driving genes (EGFR, MTOR, CCND1, and MYC) or tumor suppressor gene (RB1), with a relatively higher variation in the DN and T stages." (PMID 36914617, 2023). "GLYR1 activity was elevated in RB1 mutant cancers and taking GLYR1 activity into account abolished the negative statistical relationship between RB1 mutation and NNMT expression." (PMID 37883365, 2023). "Compared to Del-c1 and c3, the majority of cancer genes were deleted by DEL-c2, such as CDKN2A (207/528), FHIT (133/528), KDM6A (42/528), RB1 (27/528), FAT1 (23/528), NFE2L2 (13/528), ERBB4 (20/528), CUL3 (11/528), PTEN (9/528), ZNF750 (13/528) and NOTCH1 (8/528)." (PMID 36272974, 2022). "In this review, we describe the canonical and non-canonical functions of Rb1, its alteration in human cancers, and the post-translational modifications that are crucial for its regulation." (PMID 35267571, 2022). "The following most altered cancer genes were LRP1B (26%), PIK3CA (24%), CDKN2A (24%), PTPRD (15%), RB1 (13%), PDE4DIP (13%), PCLO (11%), KRAS (11%), FAT1 (10%), and RELN (10%), and these results partially overlap with the most altered genes depicted in the experimental cohort." (PMID 35330454, 2022). "When the SCLC dataset was assessed, RB1 (73%) and NOTCH1 (13%) were the most altered cancer genes." (PMID 35330454, 2022).
cancer (continued). "Two studies using whole-exome-sequencing and DNA sequencing targeting 287 cancer-related genes respectively, found that alterations in DNA repair genes may correlate with response to chemotherapy: ERCC2, ATM, RB1, and FANCC." (PMID 36322407, 2022). "Despite these studies, the numerous SL partners of RB1 have unfortunately not yet led to a targeted approach to treating RB1 defective cancers, underscoring the need for additional candidates." (PMID 33591981, 2021). "Interestingly, positively correlated loci represented cancer driver genes (MYC, PRKCD, RB1, CDK6), molecules involved in immune response (MALT1, PIK3CG), as well as cellular and hormonal signaling (HGF, PTPN13, IGF1, SMAD1, ESR1, CTGF)." (PMID 34368147, 2021). "RBP fox-1 homolog 2 (Rbfox2), a component of SGs, binds to retinoblastoma 1 (RB1) mRNA, which is closely related to cancer progression; however, the role of Rbfox2 in cancer progression remains largely unknown." (PMID 31028247, 2019). "Two other recurrently rearranged regions containing canonical cancer driver genes RB1 and CDKN2A were identified by this method but were not significant following multiple testing (FDR: q ≥ 0.2)." (PMID 30889380, 2019). "Using DNA copy number copy number data from 9744 cancer specimens belonging to 39 cancer subtypes, we show that linear deletion limitation exists, and exploit it to expose deletion-limiting genes for seven deletion targets (CDKN2A, RB1, PTEN, MAP2K4, NF1, SMAD4, and LINC00290)." (PMID 31341961, 2019). "The p16/RB1 tumor suppressor pathway is inactivated in the vast majority, if not all, human cancers." (PMID 28414317, 2017). "These segments contain known cancer genes including MYC, EGFR, ERBB2 CDKN2A, RB1 and STK11." (PMID 28686671, 2017). "Mutual exclusivity analysis with genomic alteration data showed that STK11 alterations in cancer patients rarely co-occur with CDK4, CDKN2A, CDKN2B or RB1, supporting a role for STK11 in an oncogenic pathway that is intimately associated with cell cycle function." (PMID 28205554, 2017). "Rb1 is also involved in other cellular processes such as the induction of terminal cellular differentiation, maintenance of genetic stability, protection from apoptotic insults in GBM and cancer stem cells." (PMID 27344175, 2016). "CASP8 and H19 have been previously associated with WTs, and H19 in particular has been associated with sporadic bilateral disease, whereas RB1, Mir-195 and TSPAN32 aberrations have not previously been identified in WTs, although detected in other cancers." (PMID 25763109, 2015).